CDH1 (cadherin 1)
Diseases named in the same sentence as CDH1 in open-access papers (continued):
Sharing a sentence is not in itself a finding about the gene and the disease.
tumor (continued). "The interaction between E-cadherin and EGFR (the CDH1-EGFR axis) was observed between the tumor core, boundary, and normal regions, which might lead to a significant increase in the proliferation of tumor cells via activation of the MEK/ERK signaling pathway." (PMID 41147013, 2025). "Even though not statistically significant, CDH1 reduction is also still clearly visible in the metastatic tumor cells and in the mesenchymal cells." (PMID 40332096, 2025). "For instance, some studies have reported the coexistence of both markers in the transitional EMT state, suggesting that CDH1 is not always necessary for tumor EMT." (PMID 40226617, 2025). "Cord blood from newborns (WBCs) DNA methylation of the ACSL3 promoter, Intragenic p19INK4α DNA methylation in adult blood (PBLs), CDH1, HIN1, PARPβ, and TWIST promoter DNA methylation in adult tumor tissue DNA methylation of the ESR1 promoter, BRCA1, CCND2, and DAPK." (PMID 40182693, 2025). "Early studies reporting high frequencies of CDH1 methylation were based on non-quantitative methods, and more recent research suggests that true promoter methylation in tumor cells is rare." (PMID 40757085, 2025). "According to our RNA-seq data, in addition to CDH1/CDH2 (E-cadherin/N-cadherin), ICAM1 was upregulated in both T1M1 PDAC tissues and MET-containing CM-treated PDAC cells, which indicated that METs may affect tumour cell adhesion through ICAM1." (PMID 39025845, 2024). "It is a limitation of this study that all c.760G>A carriers are, or were, at an age that does not rule out the occurrence of CDH1-related tumor development." (PMID 39596675, 2024). "Analyzing the parental MM tumors, we could detect a variable fraction of MITF−/low/CDH1−/ZEB1+/CD271+ cells, proposing the existence of a MIC subpopulation in the primary tumor mass." (PMID 38191367, 2024). "Tumour cells induced by EMT‐related signalling pathways such as WNT/β‐catenin and TGF‐β lose their epithelial characteristics because of the downregulation of CDH1 and the gain of mesenchymal properties such as increased migration activity." (PMID 38506205, 2024). "In addition, the expression of CDH1 was amplified, while that of CDH2 was attenuated in the tumours dissected from the shIGFBP7 group." (PMID 39351597, 2024). "The fibroblasts in the tumor were not stained, indicating no CDH1 expression, and the cells were light blue." (PMID 38698370, 2024). "Strikingly, this tumor and model while not annotated as ILC has a CDH1 mutation, suggesting that CASCAM authenticated a new model of ILC." (PMID 38198519, 2024). "Moreover, DNA methylation diminishes the mRNA and protein expression of caspase‐8 and E‐cadherin (Cadherin 1, CDH1) genes, enhancing the anti‐apoptotic capability of tumour cells and promoting invasion and metastasis, respectively." (PMID 39462685, 2024). "CDH1 mRNA and E-cadherin protein are not downregulated in most tumor tissues and cell lines derived from commonly occurring carcinomas." (PMID 37189027, 2023). "In agreement with recent debates on the role of E-cad in tumor progression and metastasis, our analysis demonstrates that CDH1 mRNA and E-cad protein are not downregulated in the majority of carcinomas or during tumor progression in most carcinomas." (PMID 37189027, 2023). "Interestingly, CDH1 expression was lower and VIM expression was higher in the tumor samples with high CYSLTR1 expression, although the statistical significance was not achieved, possibly due to the smaller number of patients." (PMID 36834820, 2023). "In addition, the results of an immunohistochemical study of NSL11 tumour showed that cetuximab or talazoparib resulted in a significant increase in the expression of VIM and a significant decrease in the expression of CDH1." (PMID 37441599, 2023). "The tumor suppressor PTEN is connected to WNT/CDKN1B signaling via regulation of the PI3K/AKT pathway and is also involved in morphogenesis and growth arrest by interacting with CDH1." (PMID 37313172, 2023).
tumor (continued). "For example, KCL566 (IC-NST) harboured a stop-gain CDH1 mutation plus CDH1 LOH in CSF cfDNA, with neither aberration being detected in the matched plasma, primary tumour or metastatic lymph node samples." (PMID 37973922, 2023). "This is likely due to the lack of lobular tumours in PRs ESR1LOW (3%) compared to GRs (13%) and PRs ESR1HIGH (13%) and also reflected in the percent of somatic mutations in E-cadherin in each group (CDH1 mutations 2% PRs ESR1LOW; 13% GRs and 10% PRs ESR1HIGH)." (PMID 37419892, 2023). "Tumours in cluster A were mainly described by SBS 1 and 5, lack of rearrangement signature (RS) 2, were mainly luminal (Lum) A or B, and commonly had CDH1 mutations." (PMID 37316882, 2023). "Marked hyperactivation of PI3K signalling was observed in the tumours along with expression of the cell proliferation markers Ccnd1 and pMet, the epithelial marker Cdh1 and the phosphorylation of Ybx1, but not the p-EMT marker Pdpn." (PMID 36949044, 2023). "Downregulation of both cadherins occurred in 19% of tumours, while only 7% of all tumours expressed CDH1 and lacked CDH3 expression." (PMID 37372088, 2023). "Although miR-340 and miR-185 have been reported as tumor suppressor miRNAs, the mechanism by which miR-340 and miR-185 targeting CDH1 has not been investigated, and further studies are required to determine the oncogenic regulatory mechanism." (PMID 35784532, 2022). "Repeated CDH1 sequencing of microdissected sub‐regions (with and without LCIS) confirmed the presence of the p.L214P mutation in the invasive tumor component (data not shown)." (PMID 34889530, 2022). "CDH1 is an essential intercellular adhesion molecule that inhibits tumor metastasis, and its absence is a key marker of EMT and a need for epithelial tumor cells to invade." (PMID 36003502, 2022). "In agreement with the recent TCGA study, we did not identify promoter methylation of CDH1 in any of the tumours." (PMID 35053458, 2022). "Irrespective of CDH1 expression, the migratory and invasive capacities are present in tumor cells by CDH2 expression." (PMID 36315446, 2022). "CDH1 appeared to be significantly up-regulated from the tumor initiation stage, without further alterations during the tumor development phase." (PMID 36131343, 2022). "Downregulation of E-cadherin (CDH1) and EMT is crucial for tumor invasion and metastasis." (PMID 35756648, 2022). "These were present in both dissected components (E-cadherin negative and E-cadherin aberrant) at equal frequencies of the EcadhetILC tumours, suggesting that mutation of CDH1 is an early event in these tumours." (PMID 35053458, 2022). "The quantitative polymerase chain reaction (qPCR) analysis of ARID1A and E‐cadherin (CDH1) gene expression in patient COAD tumour samples revealed a positive relationship between the two genes regardless of tumour type." (PMID 36420658, 2022). "We knocked out Tgfβr2 in p18−/−; Brca1MGKO tumor cells and found that Tgfβr2 KO led to lower expression of the EMT markers Vim, Fn, Snail, Zeb1, Slug, and higher expression of the epithelial markers including Cdh1 and Epcam." (PMID 35236825, 2022). "We found that Cdh1 (FZR1, fizzy-related 1) was highly expressed in the tumor tissues." (PMID 35627188, 2022).
tumor (continued). "Affymetrix array (U133A) data indicated that CDH1 gene expression levels were higher in the tumor T2 cell line than in the A3 cell line, non-tumorigenic." (PMID 36293530, 2022). "Moreover, LINC-ROR silencing results in the inhibition of cell proliferation, invasion, and EMT through reducing CDH1 expression and increasing the expression of ZEB1/2 and Vimentin in ESCC tumor tissues." (PMID 33745265, 2021). "In addition, over-expression of RALYL showed an obvious anti-tumor effect by inhibiting MAPK and CDH1 signaling pathways." (PMID 33437214, 2021). "This process of BHRF1+/SNHG8 high/miR-512-5p low/TRIM28high in EBVaGC directly enhances the activation of a set of tumor-promoting factors, such as proliferation-related genes (BCL-2, CCND1, PCNA, PARP1) and metastasis-related genes (Snail, VIM, CDH1, and CDH2)." (PMID 34722282, 2021). "Notably however, this over-representation of ILC was not absolute, and several tumor samples within group 3 did not contain mutations in CDH1, suggesting that chromatin state differences may contribute independently to the transcriptome differences within this class." (PMID 34922480, 2021). "Further, expression analysis of ZNF471 along with one epithelial and 9 mesenchymal markers in the GSE9750 dataset identified the downregulation of ZNF471 and CDH1 with concomitant up-regulation of ZEB1 and TWIST1 in tumor tissues when compared with normal samples (P<0.05)." (PMID 33566221, 2021). "The CDH1 expression analysis was performed by quantitative PCR (qPCR) on seven GC cell lines (NCI-N87, KATO-III, SNU-5, SNU-1, AKG, GK2, KKP) and on gastric normal and tumor tissues of eight sporadic IGC patients." (PMID 34066170, 2021). "In fact, YFP+/Cdh1– cells have tumor-initiating capacity and are able to generate both Cdh1 positive and negative cells." (PMID 34768901, 2021). "Blocking of ligand activation of Notch (all receptors) by using a soluble Notch4 exodomain (XNotch4) in BrCa xenografts promoted apoptosis and reduced tumor size and metastasis concomitantly to SNAI2 expression reduction, CDH1 upregulation, and active β-catenin suppression." (PMID 33430387, 2021). "CDH1 is a postulated tumor suppressor, and USP37 may thus act as a tumor suppressor in concert with CDH1." (PMID 34758854, 2021). "Smad4 can directly bind to the E-cadherin gene (CDH1) promoter and inhibit its transcription, and its expression can enhance the tumor cells’ resistance to apoptosis and ability to survive various stress conditions, which leads scholars to recognize it a key protein to control EMT." (PMID 32897241, 2020). "Finally, in agreement with reduced tumor cell migration upon CDH11 silencing in CAF-S1 fibroblasts, we found that these conditions had an impact on CDH1/E-cadherin protein levels in both MCF7 and T47D tumor cells." (PMID 32665033, 2020). "Furthermore, in NSCLC tumor tissues and cell lines (A549 and H1299), MALAT1 can upregulate VIM and downregulate CDH1 and is involved in the phosphorylation of AKT1, RPS6KB1, and MTOR." (PMID 32438606, 2020). "Hepatitis viral infection causes a high level of ROS-induced DNA base damage, increasing the DNA methylation at the promoter of tumour suppressor genes including Cyclin-dependent kinase inhibitor 2A (CDKN2A, or p16), E-cadherin (CDH1), and Insulin-like growth factor binding protein 1 (IGFBP-1)." (PMID 33086505, 2020). "The discrepancies between these findings and those on Cdh1 as a tumor suppressor have not been resolved." (PMID 32015681, 2020). "Interestingly, we observed that CDH11 silencing in CAF-S1 prevented this effect and kept the CDH1/E-cadherin protein level elevated at the surface of MCF7 and T47D tumor cells." (PMID 32665033, 2020).
tumor (continued). "By contrast, the inverse correlation observed between the ZEB2 and CDH1 mRNAs is maintained in all the datasets surveyed regardless of the tumor subtype involved (blue bars)." (PMID 30087437, 2019). "Here, we describe SCLC subtypes in Mycl- and Nfib-driven GEMM that include CDH1-high peripheral primary tumor lesions and CDH1-negative, aggressive intrapulmonary metastases." (PMID 31189116, 2019). "To investigate whether ALDH3A1 expression might be involved in mesenchymal phenotype development, we studied EMT markers (CDH1, Zeb1, VIM, and FN1) at the mRNA expression level in all stem-cell-like tumor cells." (PMID 31817719, 2019). "A decrease of epidermal E‐cadherin (CDH1) and a concomitant increase of vimentin (VIM) expression in the dermis indicate an enhanced tumor invasiveness, which might refer to epithelial–mesenchymal transition (EMT)." (PMID 31580518, 2019). "However, romidepsin treatment both increased the epithelial marker CDH1 expression in TU-BcX-2 K1 cells, and the gene expression patterns were similar in treatment of PDX-derived cells and tumor pieces ex vivo." (PMID 30845999, 2019). "Metastasis blockage was not related to the attenuation of the EMT program, as the expression of EMT-inducer transcription factors and the repressed expression of Cdh1 (E-Cadherin) (data not shown) was not altered in sh-SDF-1 tumor cells." (PMID 30874597, 2019). "It was found that the level of CDH1 was markedly lower in tumor tissues than that in normal adjacent tissues: 34 of 72 tumor tissues were scored as negative." (PMID 31208279, 2019). "In contrast to the suppressor role of CDH1, CDH3 may act as an oncogene and stimulates a pro-invasive character of tumor cells in the presence of CDH1 resulting in a poor prognosis." (PMID 31105876, 2019). "The novel E-cadherin variant, a truncated soluble form of E-cad resulting from a deletion of the first 34 nt in the exon 14 of the CDH1 mRNA, induces changes characteristic of the Epithelial to Mesenchymal Transition (EMT) process, a key event in tumor progression." (PMID 31781079, 2019). "Active EZH2 induces and activates, in conjunction with HMGA, tumour-promoting factors and proliferation, repressing differentiating factors such as runt-domain transcription 3 factor (RUNX3), p57 cyclin-CDK inhibitor 1C (CDKN1C), and cadherin 1 (CDH1)." (PMID 29853899, 2018). "Intriguingly, PAR-1 expression did not correlate to epithelial (tumor) cell markers Epithelial cell adhesion molecule (EpCAM), Cadherin 1 (CDH1) and Mucin 1 (MUC1)." (PMID 28173772, 2017). "We further investigated whether expression levels of CDH1 and HGS were different between non-tumor and tumor specimens." (PMID 29042578, 2017). "Downregulation of E-cadherin during EMT may be accompanied by the upregulation of mesenchymal cadherins, such as N-cadherin and cadherin-11, which allow new interactions of tumor cells with stromal fibroblasts." (PMID 29112161, 2017). "Notably, Wnt/β-catenin signaling was activated by the suppression of CDH1 in the miR-23a mediated process of TGF-β1-induced EMT and tumor invasion." (PMID 29050223, 2017). "Univariate analyses showed that lack of expression of CDH1, tumor size and nodal status were significantly correlated with worse RFS and OS (p< 0.05)." (PMID 29100362, 2017). "As illustrated by the identification of CDH1/FRA16B and MAP2K4/FRA17B, two tumour suppressors located within known fragile sites, these properties are not always biologically separated, yet in both cases, our model was able to discern the signature of selection." (PMID 29089486, 2017). "CDH1 and CTNNB1 were expressed in 52.3 % (45/86) and 36.0 % (31/86) of tumor samples, respectively." (PMID 27600761, 2016). "There was no more significant correlation of CDH1 haplotypes with clinical characteristics, including menopausal status, tumor size and lymph node involvement and histological type." (PMID 27852262, 2016).
tumor (continued). "HDGC tumours appear when complete somatic CDH1 inactivation is acquired, leading to reduced or absent E-cadherin expression." (PMID 27514667, 2016). "The ILC tumor cells are typically estrogen receptor (ER) positive and epidermal growth factor receptor 2 (HER2) negative, and often have a lost or aberrant epithelial cadherin (E-cadherin, CDH1) protein expression." (PMID 27811364, 2016). "E-cadherin (Cadherin 1), the loss of which is a hallmark of EMT, was strongly expressed in the vast majority of MTC cells in both primary tumor and metastatic sites (data not shown)." (PMID 26395490, 2015). "In our study CDH1 expression was not statistical difference between tumor gastric and normal mucosa control samples." (PMID 26334097, 2015). "Data also show that this interaction is dependent on the nature rather than the type of tumor cells and that CDH1 and IL-1β expression by tumor cells are key factors in determining the outcome of hMSC–tumor cross-talk." (PMID 26204886, 2015). "The aim of this study was to describe the morphological characteristics and the DNA methylation status of the CDKN2A,CDH1, ATM, FHIT and RAR- genes in the central and peripheral part of the tumor and the surgical margin and evaluate their prognostic significance." (PMID 24782031, 2014). "Once this process is under way in a tumor, it is typical to find a coordinated alteration in the expression of all these genes: the expression of ZEB1, ZEB2, VIM, and SNAI1 is upregulated, while the expression of CDH1 is downregulated." (PMID 25157365, 2014). "As ILBC is the key tumor entity associated with loss of E-cadherin expression, this suggests that reciprocal regulation of BCL2 is not a major mechanism of tumor development driven by CDH1 inactivation." (PMID 24023670, 2013). "The expression of miR-92 and miR-25 was correlated with the status of lymph node metastasis, most likely through the repression of the CD324-induced expression of the tumour suppressor CDH1 gene but not with the apoptosis and proliferation of ESCC cells." (PMID 23478435, 2013). "In conclusion, upregulation of BCL2 is not involved in lobular breast carcinogenesis and is unlikely to represent an important determinant of tumor development driven by CDH1 inactivation." (PMID 24023670, 2013). "In GBM, there is frequent hypermethylation of tumour suppressors (RB1, EMP3, RASSF1A and BLU), cell cycle regulators (p16INK4a and p15INK4b), DNA repair genes (MGMT, MLH1), and genes involved in tumour invasion and apoptosis (DAPK, TIMP3 and CDH1)." (PMID 22771539, 2013). "Indeed, several transcription factors that strongly repress CDH1 (such as members of Snail, ZEB and bHLH families) have recently emerged, which are now thought to be involved in tumor progression." (PMID 23548172, 2013). "Of 92 GC patients, 45 specimens showed CDH1 methylation both in their PPW and tumor tissues." (PMID 22514028, 2012). "Reduced expression of E-cadherin can be achieved in multiple ways, among which, transcriptional repression has recently emerged as a fundamental mechanism for the dynamic silencing of the E-cadherin gene (CDH1) during tumor progression." (PMID 22916288, 2012). "Interestingly, stromal cells of all tumour and normal cultures expressed detectable quantities of the SNAI I (Snail) and TCF-3 (E2A) proteins known to be transcriptional repressors of the CDH1 gene and potential inducers of EMT." (PMID 20407446, 2010). "This explains for example the occurrence of 100% methylation of the CDH1 gene in normal liver samples and the inability to detect differences in methylation levels between tumor specimens and adjacent non-neoplastic liver tissue." (PMID 21060828, 2010).